TNF (tumor necrosis factor)
Diseases named in the same sentence as TNF in open-access papers (continued):
Sharing a sentence is not in itself a finding about the gene and the disease.
depression (continued). "In the subset of depressed patients who exhibit elevated inflammatory cytokines, such as IL-6, IL-17, and TNF-α, targeted use of monoclonal antibodies against these cytokines can result in reduced anhedonia and overall depression severity." (PMID 29329256, 2018). "All these results indicate that P38 MAPK is not only the molecular target for the biosynthesis of TNF-α but is also a target for anti-inflammatory and anti-depression drug therapy." (PMID 29867510, 2018). "A limited number of studies have demonstrated increased levels of cytokines (IL-6, IL-8,TNFα) in cancer patients with depression." (PMID 30266081, 2018). "There is evidence to suggest that pro-inflammatory cytokines, including IL-1β, IL-6 and TNF-α, contribute to the onset and progression of depressive disorders." (PMID 29364170, 2018). "In a sample of 1738 MDD patients, 57 genes were identified and 92 SNPs mapped; the TNF-α rs769178 was the only gene found to be related to depression and that remained significant after correcting for multiple testing." (PMID 27555379, 2017). "It is now evident that depression is the clinical expression of peripheral cell-mediated activation, inflammation (increased levels of proinflammatory cytokines, such as IL-6 and TNF-α), and induction of oxidative and nitrosative stress pathways." (PMID 28127570, 2017). "Further in AD with depression group, the serum levels of IL 6, TNF α and 25-hydroxyvitamin D show a strong correlation with MMSE scores which implies that marked alterations of these parameters have a causal role in the progression of AD pathogenesis." (PMID 28580183, 2017). "Increased expression of pro-inflammatory cytokines IL-1β, IL-6, TNF-α, as well as interferon gamma (IFN-γ), and C-reactive protein (CRP) is repeatedly observed in patients suffering from depression and has been associated with specific symptoms of depression." (PMID 28239408, 2017). "Correlation analysis revealed that depression severity negatively correlated with IL-12 in males, and positively correlated with IL-1β and tumor necrosis factor (TNF)-α in females." (PMID 28670290, 2017). "Many studies have shown that increased plasma concentrations of interleukin (IL)-1, IL-6, and tumor necrosis factor (TNF)-α were found in major depression patients with a history of poorer response to antidepressants than in treatment-responsive patients." (PMID 28832762, 2017). "We also found a strong statistical correlation between the disease severity and the serum levels of IL 6, TNF α and 25-hydroxyvitamin D in AD patients with depression." (PMID 28580183, 2017). "This strategy was useful in a recent RCT of infliximab (a TNFα antagonist) in treatment-resistant depression." (PMID 27622678, 2017). "As a consequence, despite of the high level of cortisol, levels of TNF-α, IL-1b and IL-6 increase what is a common characteristic of major depression." (PMID 28738849, 2017). "Here, we show a moderate positive correlation between TNF-α expression level and severity of both anxiety and depression." (PMID 28928366, 2017). "The role of systemic TNF-α has been widely investigated; a high level of systemic TNF-α is associated with twofold increase in disease symptoms, including apathy, anxiety, depression, and agitation." (PMID 29137628, 2017). "Microglia are the major innate immune cell population in brain tissue and microglia-mediated inflammation is associated with the pathogenesis of various neuronal disorders, like depression, which are major cellular sources of TNF and IL-1 family of cytokines." (PMID 28694833, 2017). "Pearson partial correlational analysis revealed that there were significant associations between CM score and CRP (r = 0.21, p = 0.04), and TNFα (r = 0.23, p = 0.02), after adjusted by age, gender, race, education, and depression symptoms." (PMID 28713332, 2017).
depression (continued). "Rats with depression-like phenotype displayed increased levels of cytokines (IL-1β, IL-6, TNF-α, IL-4 and IL-10) in the PFC compared with sham-operated and rats without depression-like phenotype (P < 0.05) on day 21 after SNI surgery." (PMID 28600519, 2017). "The TNF-α rs769178 was the only gene found to be related to depression, and it remained significant after correcting for multiple testing." (PMID 27555379, 2017). "In a chronic stress-induced depression model, 10 mg/kg ketamine injection showed a rapid antidepressant effect and effectively reduced the protein expression levels of IL-6, IL-1β, and TNF-α." (PMID 28373844, 2017). "Previous studies found that Jia-Wei-Xiao-Yao-San ameliorated depression in menopausal women through increasing serum TNF-α and Dang-Gui-Shao-Yao-San improved depression-like behaviors in murine model through decreasing central arginine vasopressin." (PMID 28851349, 2017). "Of particular note, statistically moderate correlations are observed between ATP-induced TNF-α expression and various subjective parameters of pain, depression, anxiety, and QOL." (PMID 28928366, 2017). "Some studies have shown that high baseline levels (or administration) of leptin and TNF-α lead to increased rates of de novo depression/onset depression-like symptoms." (PMID 29190710, 2017). "In this study, we observed higher sera levels of TNF-α in individuals with depression and with anxiety." (PMID 26732584, 2016). "Some studies have indicated that higher blood levels of pro-inflammatory cytokines TNF-α and IL-6 in drug-free patients with depression." (PMID 27931233, 2016). "The TNF-α rs769178 was the only gene found to be related to depression and that remained significant after correcting for multiple testing." (PMID 27187381, 2016). "In summary, our results suggest that variations in maternal immune system activity during pregnancy (specifically TNF-α:IL-10) have significant sex-dependent effects on the development of major depression in adult offspring." (PMID 27244231, 2016). "It is thus unlikely that short-lived increases in cytokines playing a role in sickness behavior (such as IL-1β, IL-6, and TNF-α) will induce depression." (PMID 27504457, 2016). "Patients with depression show higher serum levels of pro-inflammatory cytokines than a normal group, including IL-1, IL-6, IL-8, IL-12, interferon-γ, and TNF-α." (PMID 27347982, 2016). "Results from trials to determine the efficacy of antiinflammatory drugs such as the use of anti-TNFα in patients with psoriasis with antidepressant potential or the adjunctive use of cyclooxygenase-2 inhibitors for treating depression have been encouraging." (PMID 26775294, 2016). "Anti-TNF-α treatment for Crohn's disease can significantly improve the patient's symptoms of depression, which is further evidence of chronic inflammation leading to psychiatric symptoms." (PMID 27478433, 2016). "In line with this, a prospective study found that the relationships between the onset of depression and physical disorders in elderly people were significant in the presence of higher TNF-α production, similar to production of IL-8, as cited previously." (PMID 27918465, 2016). "A direct correlation between sera TNF-α levels and the severity of depression symptoms (r = 0.51; p < 0.001) was observed." (PMID 26732584, 2016). "There are, at least, more three mechanisms that link the activation of the cytokine system, of which TNF-α is a part, to the pathophysiology of depression." (PMID 26732584, 2016). "Among 3024 subjects between 70 and 79 years of age, those who scored higher on a standardized depression scale also had significantly higher levels of IL-6, TNF, and CRP." (PMID 28030615, 2016). "Decline of serotonin level is generally related to depression; however, depression resulting from TNF-α-mediated IDO activation and KYN production has additional serotonin-independent effects." (PMID 27187381, 2016).
depression (continued). "It is important to consider some limitations of the study analyzing depression mediated by TNF-α, such as the small number of healthy controls included and the short follow-up period." (PMID 26732584, 2016). "A recent data found that serum TNF-α levels were significantly higher in SLE patients with depression." (PMID 27187381, 2016). "Much research has collected substantial evidence from animal studies that support the role of TNF-α in depression." (PMID 27187381, 2016). "Pro-inflammatory cytokines such as IL-1β, IL-6, TNF-α, NF-κB, and iNOS have been demonstrated to induce abnormal behaviors, such as decreased locomotor activity, exploration, and depression, which was confirmed in our experiment." (PMID 27120616, 2016). "Bupropion, a drug commonly used to treat clinical depression, decreased TNF serum levels in mice likely via increasing intracellular cAMP signaling after binding beta-adrenergic and/or D1 receptors." (PMID 27487029, 2016). "We observed that sera TNF-α levels in SLE patients were positively correlated with the severity of depression." (PMID 26732584, 2016). "Tumor necrosis factor alpha (TNF-α) is deeply related to pathogenesis of neurodevelopmental disorders, especially depression." (PMID 26732584, 2016). "This evidence includes consistent findings of increased serum levels in patients with depression of certain pro-inflammatory cytokines, particularly tumor necrosis factor-α (TNFα) and interleukin-6 (IL-6)." (PMID 25947540, 2015). "Patients with major depressive disorders have higher levels of proinflammatory cytokines, such as interleukin-6, interleukin-1, and tumor necrosis factor-alpha, than the general population." (PMID 26770976, 2015). "Several studies have reported higher serum levels of the inflammatory cytokines IL-6, IL-1 and TNF- α in depression and AD." (PMID 25793613, 2015). "SNPs in genes for IL-1, IL-6, tumor necrosis factor alpha (TNFα), cyclooxygenase 2 (COX2), superoxide dismutase (SOD), and catalase is associated with depression." (PMID 26078821, 2015). "C-reactive protein (CRP), interleukin–6 (IL–6), and tumor necrosis factor alpha (TNF-α) have previously been shown to associate with LUTS, depression and anxiety, while myeloperoxidase (MPO) has also been linked to the development of depression." (PMID 26445118, 2015). "In our experiments, the antidepressant-like effects of VAL and IMI were accompanied by a decrease in the expression of IL-1β and TNF-α in mice cortex, which is a cerebral area related to the pathophysiology of depression." (PMID 26170871, 2015). "Secondary outcomes include serum biomarkers of SCI osteoporosis (sclerostin, P1NP and β-CTX), markers of immune function (IL-6, IL-10, FGF2, INF-γ, TNF-α), neurological function, body composition, depression and quality of life." (PMID 25563584, 2015). "When reassessed for their depressive symptoms using the Hamilton Depression Scale and the Beck Depression Inventory, significantly more patients of the group receiving the TNF-α blocker showed a reduction in their depressive symptoms than in the placebo group." (PMID 26690116, 2015). "These consistent clinical findings indicate that TNF-α and IL-6 are putative biomarkers of depressive episodes and treatment response." (PMID 25793613, 2015). "With studies in depressed patients beginning to investigate the potential of inhibiting cytokines in treatment-resistant depression, there is a clear positive role for cytokines such as TNF in the regulation of mood." (PMID 26147001, 2015). "Consistently, the pivotal proinflammatory cytokines involved in sickness and depression-related behaviors following infection are IL-1β and TNF-α." (PMID 26170871, 2015). "IL-6, TNFα, IL-1β and their soluble receptors have been found to be upregulated in patients with major depression." (PMID 26793110, 2015).
depression (continued). "There was no major difference between the unadjusted regression estimates for either TNF-α or e-Selectin on incident depression and anxiety, respectively, between middle aged to older and elderly men." (PMID 26445118, 2015). "Elevations in proinflammatory cytokines like prostaglandin E2 (PGE2), C-reactive protein (CRP), TNF-α, IL-1β, IL-2, and IL-6 have been reported in major depressive disorder and, at times, have shown a dose-response with severity of depression." (PMID 26550011, 2015). "TNF-α antagonism has also been shown to improve treatment resistant depression in a subgroup of patients with high baseline inflammatory biomarkers." (PMID 26290874, 2015). "Peripheral/serum levels of IL-6 and TNF-α are increased in patients with depression, and these effects are normalized following antidepressant treatment." (PMID 25793613, 2015). "TNF-α and e-Selectin was higher in men with incident depression and anxiety, respectively, at follow-up (2.535±3.462 pg/mL vs. 2.257±1.516 pg/mL at baseline; and 38.80±16.91 ng/mL vs. 34.77±13.80)." (PMID 26445118, 2015). "Increased adiponectin levels have been found to occur due to, inhibition of TNF-α production, after remittance of depression." (PMID 26231223, 2015). "Our study also demonstrated an independent, albeit comparatively small effect, of TNF-α on incident depression / anxiety." (PMID 26445118, 2015). "On the other hand, heterogeneity remained high (I2 > 79%) in all additional analyses examining the relationship between TNF-α and major depression." (PMID 26065825, 2015). "There are several potential ways through which TNF-α can contribute to the emergence of a depression." (PMID 26690116, 2015). "Administration of IFN-alpha induces a number of other inflammatory cytokines in the periphery and central nervous system (CNS) that are elevated in depression, including interleukin-6 and tumor necrosis factor." (PMID 25638816, 2015). "The aim of the study was to determine the serum levels of CRP, IL-6 and TNF-α in elderly diabetic patients with depressive syndrome alone or with coexisting mild cognitive impairment (MCI)." (PMID 25793613, 2015). "Determine the serum levels of inflammatory markers (CRP, IL-6 and TNF-α) in elderly diabetic patients with depressive syndrome alone or with coexisting MCI." (PMID 25793613, 2015). "Depression and psychological stress are characterised by elevated levels of IL-6 and TNF-α, and IL-6 stimulates cortisol secretion by adrenocortical cells." (PMID 24731917, 2014). "Our findings supported the association between elevations of proinflammatory cytokines such as IL-6 and TNF-α and major depression." (PMID 25237578, 2014). "For instance, numerous studies have reported that pro-inflammatory cytokines, most notably interleukin-1-beta (IL-1β), IL-6, interferon-alpha (IFN-α), and tumor necrosis factor-alpha (TNF-α), are altered in major depression and stressor-based animal models." (PMID 25477784, 2014). "Serotonin-reuptake inhibitors are known to decrease TNF-α and IL-1β serum levels in patients with major depressive disorders." (PMID 25364907, 2014). "A meta-analysis performed on patients meeting the DSM criteria for major depression has shown higher concentrations of the proinflammatory cytokines TNF-α and IL-6 in depressed subjects compared to control subjects." (PMID 24723864, 2014). "In particular, SLI in basal ganglia and vascular risk factors including higher BMI levels, and inflammation markers, CRP, TNF-α, hs-CRP, and IL-6 can increase the risk for depression." (PMID 24752391, 2014). "A more recent meta-analysis by Dowlati and colleagues has supported the role of pro-inflammatory markers in depression, in particular IL-6 and tumor necrosis factor (TNF)-α." (PMID 24239712, 2014). "Elevated pro-inflammatory cytokines, such as IL-6 and TNF-α, along with CRP have been found in depressive patients; however, the association between CRP and depression is controversial." (PMID 27429271, 2014).
depression (continued). "For example, a meta-analysis of 24 studies confirmed prior reports of elevated TNFα and IL-6 in patients with major depression." (PMID 25364500, 2014). "Administration of anti-TNF-α significantly increased scores on all dimensions of quality of life and reduced depression scores measured by the HDRS, BDI and SCL-90." (PMID 23544139, 2013). "Critically, a recent study of the TNF-α antagonist infliximab in otherwise healthy patients with major depression demonstrated that the antidepressant activity of this drug was dependent on the level of inflammatory markers at baseline." (PMID 24385966, 2013). "On the other hand, several inflammatory cytokines, such as tumor necrosis factor-α (TNF-α) or interleukin-6 (IL-6), have been considered pathogenic factors associated with the mechanism of developing depression." (PMID 24138872, 2013). "TNF-α has been found to exert beneficial effects in depression-related processes, e.g., cognitive function and HC neurogenesis." (PMID 23382717, 2013). "Proinflammatory cytokines, such as IL-1β, IL-6, and TNF-α, also elicit adverse behavioral effects (fatigue, soporific effects) and symptoms of anxiety and depression." (PMID 24348675, 2013). "Kubota and colleagues found elevated TNF-α and IL-6 in people with HF, while other studies reported similar findings in patients with depression and HF." (PMID 22919538, 2012). "Elevated levels of proinflammatory cytokines, specifically IL-6, TNF-α, as well as C-reactive protein, seem to have a broad role in HF, depression, and CogI." (PMID 22919538, 2012). "Within the PD sample, high levels of both sIL-2R and TNF-α were significantly associated with more severe symptoms assessed by means of FACIT and HAD (depression and anxiety subscales)." (PMID 23082161, 2012). "The aim of this study was to examine serum levels of the proinflammatory cytokines interleukin 6 (IL-6) and tumor necrosis factor α (TNFα), and the anti-inflammatory cytokine IL-10, in perimenopausal women suffering from depression." (PMID 22490187, 2012). "Recent meta-analyses and recent publications have confirmed increased levels of PICs in human depression particularly IL-6, TNFα, and IL-1, and CMI activation, evidenced by higher levels of neopterin and soluble IL-2 receptors (sIL-2Rs)." (PMID 22747645, 2012). "In the subsequent regression analyses we showed that sIL-2R (and less robustly TNF-α) explained a unique and substantial part of the variance in depression scores, and that this relationship was statistically significant." (PMID 23082161, 2012). "Proinflammatory cytokines, such as interleukin 6 (IL-6) and tumor necrosis factor α (TNFα) have been considered as key neuromodulators of behavioral, neuroendocrine and neurochemical features of depressive disorders." (PMID 22490187, 2012). "This study indicates a possible association between TNF-α and two frequent and major co-morbidities in COPD; i.e., depression and fatigue." (PMID 21208443, 2011). "A cluster of cytokines including interleukin-1 beta (IL-1β), IL-2, IL-6, interferon-gamma, and tumor necrosis factor alpha (TNFα) have been reported to correlate with depression symptoms." (PMID 21864357, 2011). "A multivariate linear model of all biomarkers showed that TNF-α only had a positive correlation with BASDEC depression score (p = 0.007)." (PMID 21208443, 2011). "In conclusion, our data indicate an association between TNF-α and two major co-morbidities in COPD; i.e., depression and fatigue." (PMID 21208443, 2011). "TNF-α remained positively correlated with depression (p = 0.024) after further adjusting for TNF-α-R1, TNF-α-R2, 6MWD, FEV1%, and pack-years." (PMID 21208443, 2011). "Activation of the innate immune system of the brain contributes to pathophysiologic changes that occur in depression due to the generation of inflammatory mediators including nitric oxide, via iNOS, and pro-inflammatory cytokines such as IL-1β and TNFα." (PMID 21306618, 2011).